MPO (myeloperoxidase)
Diseases named in the same sentence as MPO in open-access papers (continued):
Sharing a sentence is not in itself a finding about the gene and the disease.
vasculitis (continued). "Alternative to inducing MPO-specific immunosuppression, other attractive cell therapies such as stem cells would desirably suppress anti-MPO autoimmunity and vasculitis without being rejected or producing major adverse effects." (PMID 34394071, 2021). "Antineutrophil cytoplasmic antibody (ANCA)-associated vasculitis (AAV) is a systemic autoimmune disorder involving a pauci-necrotizing small-sized vasculitis, in which ANCA targeting myeloperoxidase (MPO) and proteinase 3 (PR3) participate in the pathogenesis of the disease." (PMID 34950150, 2021). "Stem cells have never been tested as a treatment in this disease, but we are currently exploring the therapeutic efficacy of hAECs and their exosomes in pre-clinical models of MPO-AAV, which will pave the way for this therapy to be clinically tested in vasculitis patients." (PMID 34394071, 2021). "These previous results are consistent with our conclusion that the alternative pathway of complement is not important in anti-MPO vasculitis in our hands." (PMID 36751530, 2021). "Moreover, previous research revealed that vasculitis patients are more likely to show increased PR3 expression; this phenomenon can be explained by disruptions in the epigenetic silencing of the MPO and PR3 genes in affected patients." (PMID 33746569, 2021). "Vasculitis, a shared condition between fatal COVID-19 and vascular autoimmune diseases such as Anti-neutrophil cytoplasmic autoantibody (ANCA) vasculitis, is featured by elevation of MPO and PRTN3 levels." (PMID 34276672, 2021). "We performed a retrospective review of clinical records of MPO-AAV patients with renal involvement without AS at the onset of vasculitis who were treated in three hospitals and three dialysis clinics." (PMID 33481903, 2021). "Despite high levels of anti-MPO (greater than 100 U/mL) measured in the newborn immediately after birth, he did not develop any signs of vasculitis." (PMID 34717662, 2021). "Exogenous neutrophil infusions allowed the development of anti MPO vasculitis and GN confirming the non-redundant role played by neutrophils in the disease." (PMID 33790907, 2021). "Elevated levels of ADAM metallopeptidase domain 17 (ADAM17) and α1-trypsin polymers have been reported in PR3-ANCA vasculitis, while the expression of ADAM17 in MPO-ANCA vasculitis has not been tested so far." (PMID 33023023, 2020). "Compared to patients without PN, patients with PN had a higher erythrocyte sedimentation rate, C-reactive protein, rheumatoid factor, Birmingham vasculitis activity score (BVAS), and positivity of myeloperoxidase-antineutrophil cytoplasmic antibodies (MPO-ANCA)." (PMID 32714994, 2020). "Some authors have reported the outcome in 14 patients with very severe renal impairment (eGFR< 20 ml/min/1.73 m2) due to AAV or ANCA negative vasculitis; this multicentre study showed 100% achieving remission and an improvement in kidney function in most of cases (both MPO and PR3 vasculitis)." (PMID 31088509, 2019). "ANCA-positive IgGs (obtained from 5 active MPO-ANCA- and 3 active PR3-ANCA-positive vasculitis cases) were used to assess whether ANCA would induce respiratory burst in MIF-treated neutrophils." (PMID 31248381, 2019). "Notwithstanding, any testing strategy applicable to vasculitis should be able to identify relevant ANCA target antigens (PR3 and MPO), since these correlate best with the clinicopathological aspects, disease activity, propensity for relapse, and response to therapy." (PMID 32185292, 2018). "Pronounced (positive and inverse) correlations among all measured variables were observed in PR3-AAV but not in MPO-AAV or ANCA-negative vasculitis." (PMID 30533405, 2018). "Detection of ANCA in vasculitis is based on primary screening by immunofluorescence test (IFT) on ethanol-fixed neutrophils, and positive indirect immunofluorescence (IIF) test should always be followed by specific PR3- and MPO-ANCA immunoassays." (PMID 32185292, 2018).
vasculitis (continued). "In addition, we had to exclude the other reasons of MPO-ANCA positivity: inflammatory bowel diseases, rheumatoid arthritis, infections (endocarditis, tuberculosis, and amebiasis), drug-induced vasculitis (hydralazine, propylthiouracil), and malignancy." (PMID 28243232, 2017). "It is a debatable point that previous learning from the Hanshin-Awaji earthquake might allow us to screen the MPO-ANCA titer and to diagnose the vasculitis for many outpatients visiting our hospital after this disaster." (PMID 28498830, 2017). "Both properdin and the lectin pathway are therefore excluded as the initiator of AP activation in anti‐MPO vasculitis." (PMID 27235854, 2016). "The initiator of AP activation in anti‐MPO vasculitis is not known, and we have excluded both properdin and the lectin pathway as candidates." (PMID 27235854, 2016). "The patient had no clinical signs of recurring renal disease or vasculitis and anti-MPO ANCA had further decreased to 45 IU/mL." (PMID 26266064, 2015). "Subsequent translocation of ANCA antigens (e.g., MPO/PR3) to the cell surface of neutrophils and expression of adhesion molecules by endothelial cells result in cell adhesion, release of reactive oxygen species, vasculitis, and endothelial apoptosis." (PMID 26266064, 2015). "The relation of ITP with vasculitis in our patient is not clear because it occurred at a moment when MPO-ANCA titers were low but ITP was also rapidly followed by recurrence of vasculitis in the form of pulmonary fibrosis." (PMID 26266064, 2015). "In the current study, only patients with MPO-ANCA were included, since previous experimental and clinical studies that investigated the role of the complement system in the pathogenesis of AAV focused mainly on MPO-ANCA-positive vasculitis." (PMID 25994214, 2015). "It has been suggested that ANCA in Asian patients with GPA are more likely secondary to antibodies to myeloperoxidase while Caucasian patients have anti-PR3-ANCA even if the vasculitis is not GPA." (PMID 25815014, 2015). "Hence, our results support the hypothesis that the generation of HOCl through a MPs-associated MPO/H2O2/Cl-–dependent mechanism may extend the endothelial damage induced by activated neutrophils, contributing to the severity of inflammatory diseases such as vasculitis and sepsis." (PMID 24915973, 2014). "Sera from 17 patients with PTU-induced AAV, 17 patients with PTU-induced MPO-ANCA but without clinical evidence of vasculitis, and 64 patients with primary AAV were collected at presentation." (PMID 24252385, 2013). "Meanwhile, the prevalences of antibodies against the proteinase 3, cathepsin G, lactoferrin, HLE, and azurocidin were significantly higher in patients with PTU-induced vasculitis than those in patients with PTU-induced MPO-ANCA but without clinical vasculitis." (PMID 24252385, 2013). "We also found that PTU-induced AAV patients had higher reactivity against the H1 fragment compared with patients with PTU-induced MPO-ANCA but without clinical vasculitis." (PMID 24252385, 2013). "This study mapped epitopes of MPO-ANCA in sera from patients with PTU-induced MPO-ANCA (with or without vasculitis) and primary AAV, aiming to analyze certain epitopes associated with the development of PTU-induced AAV." (PMID 24252385, 2013). "Fifteen of 17 patients with PTU-induced vasculitis were serum AECA positive, whereas none of the patients with PTU-induced MPO-ANCA but without clinical vasculitis was AECA positive (88.2% versus None; P < 0.001)." (PMID 24252385, 2013). "Consistently, the current study found that sera from patients with PTU-induced AAV recognized significantly more fragments compared with sera from PTU-induced MPO-ANCA without clinical vasculitis." (PMID 24252385, 2013). "The number of fragments recognized in PTU-induced AAV was significantly more than that in PTU-induced MPO-ANCA but without clinical vasculitis (2(0 to 4) versus 1(0 to 2), P = 0.026)." (PMID 24252385, 2013).
vasculitis (continued). "Our previous study found that among patients with PTU-induced ANCA, the prevalence of serum MPO-ANCA was significantly higher in patients with clinical vasculitis than that in patients without clinical vasculitis." (PMID 24252385, 2013). "Nevertheless, bringing into question the pathogenic role of anti-MPO and anti-CAWS antibodies, we found that similar to the WT mice (n= 10), 100% of B cell-deficient mice (Igh−/− mice; n= 8) developed vasculitis, after CAWS administration (data not shown)." (PMID 23074996, 2012). "Although ANCA is autoantibodies characteristic of vasculitis diseases, PR3-ANCA and MPO-ANCA are known to be negative in some kinds of vasculitis such as polyarteritis nodosa and aortitis syndrome." (PMID 19594951, 2009). "Both myeloperoxidase (MPO) antineutrophil cytoplasmic antibody (ANCA) and proteinase 3 (PR3) ANCA levels were within normal reference ranges, suggesting no active vasculitis or ANCA-associated autoimmune disorder, ruling out a vasculitic cause for this presentation." (PMID 40718213, 2025). "Eosinophilia may point toward EGPA but can also occur in myeloperoxidase (MPO)-positive vasculitis without classical features of EGPA." (PMID 41306180, 2025). "These interventions may have had additional effects, and our data suggest that inhibition of NET formation may not be sufficient to inhibit disease in murine anti-MPO vasculitis." (PMID 36154801, 2023). "However, we confirmed that there was no benefit with AZD5904 administration when anti-MPO vasculitis was induced without coadministration of G-CSF." (PMID 36154801, 2023). "Thus, our results show that while myeloid-specific Mcl1 is required in this model of anti-myeloperoxidase vasculitis, myeloperoxidase inhibition is not protective." (PMID 36154801, 2023). "The fact that some patients with remission PR3- and MPO-AAV, despite a Birmingham Vasculitis Activity Score Version 3 (BVAS) of 0, still had slightly elevated CRP levels and persistent low-titer ANCAs suggests that some residual inflammation may explain this observation." (PMID 36125911, 2022). "They found that the positive anti-myeloperoxidase-ANCA group was mainly characterized by vasculitis in epineural vessels, while the negative anti-myeloperoxidase MPO-ANCA group was mainly characterized by eosinophil infiltration, suggesting the existence of at least two distinct mechanisms." (PMID 36388946, 2022). "IPF with ANCA positivity could represent a distinct phenotype characterized by ANCA-positive conversion (mostly anti-MPO), the presence of ground-glass attenuation around honeycombing on chest HRCT, and possible subsequent development of clinical vasculitis in an IPF patient." (PMID 35244078, 2022). "In this study, the patients with positive MPO-ANCA showed a significantly higher ratio of biopsy-proven vasculitis than the patients with negative ANCA (53.8% vs. 17.7%, p = 0.01), but eosinophilic infiltration and granulomas were both comparable between the groups." (PMID 35833130, 2022). "Moreover, five of nine patients with VTE in the PR3-ANCA group exhibited anti-plasminogen antibodies; in contrast, these were absent in patients with MPO-ANCA vasculitis and thrombosis." (PMID 33909191, 2021). "Glomerular immune complex deposition is not a feature of anti-MPO vasculitis." (PMID 36751530, 2021). "ANCA directed against proteinase 3 (PR3) and myeloperoxidase (MPO) have the ability to activate neutrophils, increasing their ability to adhere to the endothelial cells, which in turn induces oxygen release and lithic enzymes that damage blood vessel walls, producing vasculitis." (PMID 33215484, 2020). "Indeed, ANCA, PR-3, and MPO antibodies can all be positive inpatients with monoclonal gammopathy in the absence of vasculitis." (PMID 31043084, 2019). "The Venn diagram showed that no SNPs overlap between PR3-ANCA and MPO-ANCA vasculitis." (PMID 30795559, 2019). "No noteworthy comparison was observed in both MPA and MPO-ANCA vasculitis." (PMID 30795559, 2019).
vasculitis (continued). "No overlapping SNPs were found between PR3-ANCA and MPO-ANCA vasculitis." (PMID 30795559, 2019). "MPO-ANCA reduced secretion of antiinflammatory IL-10 by monocytes (and may hence further foster local inflammation) and also induced development of macrophages that instruct CD4+ T cells, which could contribute to the tissue fibrosis observed in vasculitis." (PMID 28138552, 2017). "In addition, transfer of a T cell-enriched (>99 %) splenocyte fraction from MPO-immunised MPO−/− mice did not reproduce the vasculitis seen after unfractionated splenocyte transfer (a preparation comprising approx 25/65 % T/B cells, respectively)." (PMID 25056155, 2014). "Serum samples from these 17 PTU-induced AAV patients in active stage, 12 PTU-induced AAV patients in remission, and 17 PTU-induced MPO-ANCA-positive patients but without clinical evidence of vasculitis were demonstrated to recognize all the six constructed linear protein fragments." (PMID 24252385, 2013). "Compared with sera from patients with PTU-induced MPO-ANCA but without clinical vasculitis, sera from PTU-induced AAV patients showed significantly higher reactivity against the H1 fragment of MPO [OD values: 0.17(0.10 to 0.35) versus 0.10(0.04 to 0.21), P = 0.038]." (PMID 24252385, 2013). "It is reasonable to investigate whether the difference of epitope(s) of MPO contribute to the development of these two different phenotypes (that is, with or without vasculitis)." (PMID 24252385, 2013). "Sera from 15 (88.2%) of 17 patients with PTU-induced AAV and 11 (61.1%) of 18 patients with positive PTU-induced MPO-ANCA but without clinical vasculitis could recognize at least one peptide." (PMID 24252385, 2013). "Moreover, in our previous cross-sectional study, it was found that among patients with PTU-induced ANCA, only about one in five developed clinically evident vasculitis; even in those who were MPO-ANCA positive, not all developed clinically evident vasculitis." (PMID 24252385, 2013). "Finally, although Coxiella burnetii has been associated with secondary vasculitides (predominantly mixed cryoglobulinemic vasculitis), MPO-ANCA positivity has not been specifically documented in C. burnetii-related vasculitis, further supporting MPA over an infectious mimic." (PMID 41515620, 2026). "Even though cytokine levels were not investigated in our case, it is possible that post-MIS-C MPO-ANCA vasculitis could be attributed either to the initial paramount increase of IL-17 and IFN-gamma levels during MIS-C onset or to the persistently high cytokine levels at vasculitis diagnosis." (PMID 39280366, 2024). "In Asian countries, the prevalence of MPO/PR3-ANCA in patients with ANCA-associated vasculitis (AAV) is much higher than in European countries, but there has been no report about MPO-ANCA-associated vasculitis in ADPKD patients or any association between MPO-ANCA and ADPKD." (PMID 23617397, 2013). "A retrospective study of 190 Chinese patients with myeloperoxidase (MPO)-AAV found that the baseline SII was positively correlated with CRP and ESR, but not with the Birmingham Vasculitis Activity Score (BVAS)." (PMID 40852721, 2025). "These T cells provide help to PR3- or MPO-reactive B cells, leading to the emergence of anti-PR3 and anti-MPO antibodies: a phenomenon that by itself is not sufficient to lead to vasculitis." (PMID 39658634, 2025). "Anti-MPO and anti-PR3 levels at the moment of vasculitis diagnosis are related with disease severity but not with disease outcome or vasculitis recurrence." (PMID 37676628, 2024). "Although she had a previous history of eosinophilic pneumoniae and myeloperoxidase (MPO) ANCA positivity, there were no apparent findings of vasculitis before the initiation of dupilumab." (PMID 37076824, 2023). "Among patients with renal involvement, patients with positive MPO-ANCA had higher proportions of female, fever, biopsy-proven vasculitis, and faster ESR; patients with negative ANCA developed more skin and cardiac involvement." (PMID 35833130, 2022).
vasculitis (continued). "Of 138 MPO-AAV patients, 39 did not have echocardiography results at 1 year after or at the onset of vasculitis; one patient experienced AS at the onset of vasculitis, and another patient did not have precise information." (PMID 33481903, 2021). "In case of a high clinical suspicion of vasculitis and a negative test result in PR3- and MPO-ANCA immunoassay, the revised international consensus on ANCA testing recommend performing IIF or a second antigen-specific immunoassay." (PMID 31544837, 2019). "In MPO-AAV, disease activity scored by PVAS or PGA had a pronounced negative correlation with Hb concentration, while in ANCA-negative vasculitis no inflammatory markers correlated with PVAS or PGA." (PMID 30533405, 2018). "None of the IBD and SpA patients recognized myeloperoxidase antigen, elastase, lactoferrin, proteinase 3, or cathepsin G, indicating that p-ANCA is a different antigen that is specifically recognized in vasculitis." (PMID 29213287, 2017). "Animal models also exist that recapitulate the main phenotypic features of MPA using MPO-ANCA; on the other hand, the pathogenicity of PR3-ANCA has not clearly been demonstrated in animal models of vasculitis." (PMID 28476172, 2017). "She does not have any clinical manifestations of vasculitis, her ANCA is negative as are anti-PR-3 and anti-MPO antibodies, and ANCA vasculitis is rare in young African American women." (PMID 27504208, 2016). "Among the patients with PTU-induced MPO-ANCA, except for only one with clinical vasculitis had positive ANA, all the patients with and without clinical vasculitis were negative for ANA, anti-dsDNA, anti-histone, and anti-Sm antibodies." (PMID 24252385, 2013). "We compared the MPO epitopes between the 17 patients with PTU-induced AAV and the 17 patients with PTU-induced MPO-ANCA but without clinical vasculitis." (PMID 24252385, 2013). "ILD is increasingly recognized in a subgroup of patients with AAV, especially those with MPO-ANCA, and may even occur in the absence of vasculitis." (PMID 41438740, 2025). "Although it was previously thought that dual positivity for MPO and PR3-ANCA is characteristic of cocaine/levamisole-induced vasculitis, a recent case series analysis suggested this might not necessarily be pathognomonic." (PMID 39114241, 2024). "For the AAV group, neither myeloperoxidase (MPO) or proteinase-3 (PR3) ANCA levels (rho = 0.09, p = 0.63 and rho = −0.035, p = 0.85, respectively) nor the Birmingham Vasculitis Activity Score (BVAS) (rho = 0.017, p = 0.93) significantly correlated with anti-oxLDL antibody levels." (PMID 37240332, 2023). "In summary, this EGPA cohort from China revealed that the patients with positive MPO-ANCA showed an increased disease activity, higher proportions of renal lesions, and biopsy-proven vasculitis, whereas the patients with negative ANCA had more cardiac involvement and asthma." (PMID 35833130, 2022). "A kidney biopsy exhibits prognostic value, while in cases with clinical presentations that are compatible with AAV, a positivity of either PR3- or MPO-ANCA and a low suspicion for secondary vasculitis forms, treatment can be initiated without a biopsy-confirmed diagnosis." (PMID 33909191, 2021). "Indeed, in this study, MPO-ANCA(+) vasculitis, apart from the impaired renal function, seemed to be placed more closely to ANCA(-) vasculitis rather than PR3-ANCA(+), in terms of the rest clinical and laboratory characteristics." (PMID 35127750, 2021). "Our analysis found no genetic overlap of MPO-ANCA and PR3-ANCA vasculitis." (PMID 30795559, 2019). "Even in cases with negative MPO-ANCA or 1+, this result may occur in treated, inactive or relapsing vasculitis, and can therefore not be considered irrelevant." (PMID 30057255, 2019).